KRAS (KRas proto-oncogene, GTPase)
Diseases named in the same sentence as KRAS in open-access papers (continued):
Sharing a sentence is not in itself a finding about the gene and the disease.
cancer (continued). "Nevertheless, KRAS inhibition alone may be insufficient in some settings, as cancer cells often activate parallel survival pathways." (PMID 41322195, 2025). "Thus, COA4 represents a potential therapeutic target for inhibiting metastasis in KRAS‐driven cancers." (PMID 40936169, 2025). "Whether this dual role uniquely impacts the immune-mediated response in KRAS-driven cancers remains to be seen." (PMID 40867322, 2025). "Moreover, through an anchoring-independent three-dimensional growth inhibition assay, we found that SIAIS562055 significantly impeded the growth of KRAS-mutant cancer cells, while having a minimal effect on KRAS-WT cells." (PMID 39437162, 2025). "BI 2865, a newly developed non-covalent, selective inhibitor targeting the inactive state of KRAS, shows broad preclinical efficacy against diverse KRAS mutants, supporting the potential of pan-KRAS inhibition as a therapeutic strategy in KRAS-driven cancers." (PMID 41153346, 2025). "Of note, several pathways that could logically impact tumorigenesis were differentially active with age, including reduced MAPK signaling in aged cancer cells, which has a critical role in driving proliferation downstream of oncogenic KRAS." (PMID 41188600, 2025). "While KRAS mutations are relatively rare, they have been reported in subsets of Noonan and cardiofaciocutaneous syndromes, underscoring the systemic impact of aberrant RAS signaling beyond cancer." (PMID 41514544, 2025). "Moreover, investigating the broader metabolic networks and their interactions with oncogenic pathways in KRAS-mutant cancers will be essential to fully harness the potential of metabolic interventions." (PMID 40437561, 2025). "Specifically, NAT10 may exert a stronger cancer-promoting effect in KRAS mutant cells compared to KRAS wild-type cells." (PMID 39905540, 2025). "Moreover, given the high levels of KRAS expression in cancer, there is considerable interest in developing therapies that target HCC with KRAS expression." (PMID 40390765, 2025). "Therefore, improving preclinical models, such as organoids, is crucial for more effectively targeting oncogenic drivers like KRAS and its subtypes in cancer research and therapy development." (PMID 40275403, 2025). "Research on the mechanism and therapeutic solution in KRAS/KEAP1 mutant cancer is limited, maybe because of the relatively low mutant rate." (PMID 40611261, 2025). "Considering that antitumor T cells are often found at low frequencies in patient samples, we anticipate that our technology would pair well with therapeutic cancer vaccines containing one or a few known antigens, such as the KRAS or neoantigen vaccines currently in trials." (PMID 41202121, 2025). "KRAS, one of the three RAS genes, can be selectively spliced to produce approximately 12 kDa‐long KRAS4A and KRAS4B with nearly identical G structural domains and is one of the common genetic mutations in many human cancers, playing a central role in cancer biology." (PMID 40134951, 2025). "This functional synergy between NRF2 and KRAS supports the hypothesis that these oncogenes jointly reprogramme the metabolism of cancer cells." (PMID 40567499, 2025). "In conclusion, this is the first study to demonstrate that direct pharmacologic inhibition of KRAS shows antitumor activity in preclinical models of cancer with KRAS WT amplification, suggesting a novel therapeutic concept for patients with cancers bearing this KRAS alteration." (PMID 39711431, 2025).
cancer (continued). "The Krystal-1 trial (NCT03785249) demonstrated the efficacy of adagrasib in KRAS-mutated cancers, with no new safety concerns in the phase II portion of the trial." (PMID 41309533, 2025). "Other potential commonalities between these two cancer types, as well as the intricate gene networks regulated by KRAS mutations, have not been explored." (PMID 40013338, 2025). "Single-cell analysis of localized Ras-LOCKR-S demonstrated that a subpopulation of KRas-G12C-driven cancer cells treated with Ras-G12C–GDP inhibitors increased Golgi-localized WT H/NRas activity, which correlates with rebound MAPK signaling and drug-resistant cell growth." (PMID 39103633, 2025). "We used the high-throughput cellular viability PRISM assay to test the antiproliferative activity of BI-2493 in a larger cancer cell line panel than in our previous work, which allowed us to evaluate less frequently occurring genetic alterations such as KRAS WT amplifications." (PMID 39711431, 2025). "Thus, it is possible that KRas-G12C-driven cancer cells treated with Ras-G12C inhibitors adapt by reorganizing Ras signaling to enable drug resistance." (PMID 39103633, 2025). "Thus, the discovery that the ERK/MAPK cascade is a key effector of KRAS-driven cancer growth fueled a second major approach of indirectly targeting KRAS." (PMID 40829181, 2025). "This binding may deactivate the oncogenic activity of KRAS by hindering the binding of GEF molecules to the switch regions and reducing the levels of activated NF-κB, ultimately making cancer cells more susceptible to radiotherapy." (PMID 40141193, 2025). "Furthermore, we observed the upregulation of various cancer-associated hallmarks in cells expressing these high-risk genes, including TNF-alpha, UV response, angiogenesis, MYC, and KRAS." (PMID 40362553, 2025). "However, recent studies have shown that various immunotherapeutic approaches exhibit promising efficacy in targeting KRAS-driven cancers." (PMID 40429703, 2025). "KRAS G12D mutations can upregulate NRF2 transcription through stimulation of the TPA response element (TRE) via MAPK signaling, providing a protective advantage to the cancer cells against chemotherapy-induced ROS." (PMID 39857784, 2025). "KRas G12D is one of the most common oncogenic drivers in human cancers." (PMID 40837237, 2025). "Recognizing these challenges, we hypothesized that combining irinotecan‐loaded silicasomes, which locally induce ICD, with spleen‐targeting LNPs delivering KRAS mRNA may be able to synergistically activate the PDAC cancer immunity cycle." (PMID 40498983, 2025). "However, LG and HG PanIN lesions are present in cancer-free elderly individuals, indicating that additional genetic steps are essential to unleash the oncogenic driver function of mutant KRAS." (PMID 40829181, 2025). "Moreover, activation of common pathways in some cancers, such as KRAS pathway, activation of IL6-JAK-STAT3/STAT5 pathway and activation of TNFα signaling pathway via NFkB were remarkably correlated." (PMID 39925804, 2025). "Cancer Hotspot analysis showed unique somatic pathogenic variants in SMAD4 and ERBB2 and a variant of unknown significance (VUS) in PTPN11 in T2 and in KRAS in T3." (PMID 40956995, 2025). "The KRAS gene encodes a member of the Ras family of small GTPases, alongside its paralogs Harvey rat sarcoma viral oncogene (HRAS) and neuroblastoma rat sarcoma viral oncogene (NRAS), all of which are commonly mutated in cancer." (PMID 40805153, 2025).
cancer (continued). "Similarly, mutations in KRAS often result in the constitutive activation of the RAS/MAPK pathway, which is implicated in several cancer types." (PMID 40450370, 2025). "However, future studies are warranted to develop targeted therapies or combination therapies leveraging the immune microenvironment characteristics and metabolic targets in KRAS-driven cancers." (PMID 41184283, 2025). "Herein, we evaluate ADT-007, a novel pan-RAS inhibitor, and benchmark its potency and selectivity against other known apoptosis inducers, bortezomib and YM155, for killing KRAS-mutant cancer cells using 3D BEST derived from KRAS-mutant (HCT-116) and WT RAS (HT29) CRC cells." (PMID 41008802, 2025). "This gene editing tool has also been utilised in targeting mutant KRAS-driven cancers." (PMID 39820726, 2025). "However, with the recent advancements in new small molecules that can reversibly or irreversibly bind to KRAS with high affinity, we have a possible impossibility for the treatment of cancers highly reliant on KRAS, such as PDAC." (PMID 40002297, 2025). "Indeed, WEE1 has been shown to be a key dependency in KRAS-mutant cancers, and co-inhibition of KRAS with WEE1 and other cell-cycle and mitotic proteins has been identified as promising combination strategies through large-scale screening efforts." (PMID 39807828, 2025). "Our study showed that RCC1 could mediate the down-regulation of SIRT3 expression in KRAS-driven cancer cells." (PMID 41391757, 2025). "These mutations either reactivate signaling through KRAS or bypass KRAS by activating parallel pathways that drive cancer cell growth but in either case may increase RS and DNA damage." (PMID 39807828, 2025). "Mutant Ras oncoproteins, particularly KRAS, are among the most prevalent drivers of cancer." (PMID 41436723, 2025). "As an example, mutations of codon 13, but not codon 12, of KRAS were associated with a significant reduction in cancer‐specific survival in women, but not in men." (PMID 40727998, 2025). "On the cellular level, it substantially reduced downstream ERK and AKT phosphorylation, inhibited the viability of cancer cells harboring the KRAS p.G12C mutation, and demonstrated high selectivity over non-KRAS p.G12C cancer cells." (PMID 40304209, 2025). "However, targeting effector proteins in KRAS-mutant cancers proved ineffective, as resistance emerged through the activation of alternative pathways or additional mutations in those effectors." (PMID 41294676, 2025). "YAP is crucial for the progression of KRAS‐mutant pancreatic neoplasia to invasive cancer." (PMID 40895190, 2025). "The strategic integration of ferroptosis inducers with KRAS inhibitors may herald a novel paradigm in cancer therapeutics." (PMID 40390765, 2025). "Also, silencing LDHB did not decrease SLC7A11 expression in KRAS wild-type cancer cells; in fact, an increase in SLC7A11 was observed in HT1080 cells after LDHB silencing, but LDHB silencing still sensitized KRAS wild-type cancer cells to GPX4 inhibition." (PMID 40090955, 2025). "This consistency across studies strengthens the hypothesis that KRAS-mutant cancers may represent a distinct subset with specific implications for immunotherapy strategies." (PMID 41515496, 2025). "However, the development of covalent inhibitors capable of binding irreversibly to the cysteine residue unique to KRAS G12C marked a breakthrough in cancer therapeutics." (PMID 41373672, 2025). "Two recent meta-analyses investigated the activity of KRAS G12C inhibitors across cancers." (PMID 40940900, 2025). "Sotorasib significantly decreased the ratio of the GTP-bound form of KRAS/G12C but not KRAS/wild-type and other cancer-associated KRAS mutants such as KRAS/G12D, G12V, and G13D." (PMID 40286847, 2025). "Expression changes for the majority of genes in CRC mutant vs KRAS wild type cancer cell lines." (PMID 40013338, 2025). "Oncogenic KRAS, a notorious driver of cancer progression, remains a therapeutic challenge." (PMID 40390765, 2025).
cancer (continued). "For a set of genes, qRT–PCR performed on colon and pancreatic representative cancer cell lines showed concordant expression trends when comparing colon‐dominant KRAS mutants versus WT KRAS and dominant pancreatic KRAS mutants versus WT KRAS, as expected according to in silico analyses." (PMID 40013338, 2025). "This is underscored in some cancers, where the KRAS oncogene can drive autophagy addiction." (PMID 40657934, 2025). "In this study, we investigate the radiomic signature of KRAS mutations and the transferability of classification models in NSCLC by taking a publicly available NSCLC dataset from The Cancer Imaging Archive (TCIA) and a local dataset into account for model training and testing." (PMID 39860023, 2025). "Addressing KRAS-induced immune alteration may facilitate precision medicine strategies, enhancing patient outcomes in KRAS-mutant cancers." (PMID 40075634, 2025). "For decades, researchers have identified KRAS as an important therapeutic target for cancers." (PMID 41184244, 2025). "Given that cancer cells rely on these metabolic changes to sustain cell growth and survival, targeting these processes may represent a promising therapeutic strategy for KRAS-driven cancers." (PMID 39806421, 2025). "Finally, an analysis integrated cancer cell line dependencies, gene actionability and patient genomic data to identify EGLN1 as a therapeutic target, especially in KRAS-mutated LUAD." (PMID 40849356, 2025). "The combination of atypical BRAF and other atypical Ras mutations (in KRAS, NRAS, or NF1) is consistent with a “mini-driver” model in which some cancers acquire sufficient Ras activation through a two-step process rather than a single “hit” at BRAFV600E or one of the common KRAS hotspots." (PMID 39751654, 2025). "Mutant KRAS regulates cancer immune escape in KRAS-driven tumors by enhancing PD-L1 expressions." (PMID 40075634, 2025). "This uncovered a potential role for KRAS in regulating cancer epigenetics." (PMID 40707783, 2025). "KRAS is a proto-oncogene that functions as a key mediator of the RAS signaling pathway, which drives cell growth and proliferation; specifically, codon 12 is recognized as a mutational “hotspot” across many cancer types." (PMID 40896434, 2025). "Not all cancer cells with KRAS mutations require KRAS activation to maintain their viability, which is strongly associated with intrinsic resistance to KRAS G12C inhibitors." (PMID 40597785, 2025). "Unfortunately, cancer patients who experience an objective response or stable disease may progress after treatment with KRAS G12C inhibitors." (PMID 40597785, 2025). "Overall, due to its favorable pharmacodynamic profile and initial signs of efficacy, divarasib is generating significant interest in the scientific community, and there is hope that it will deliver more substantial benefits for patients with KRAS G12C-mutant cancers." (PMID 40940900, 2025). "Targeting SOS1 has emerged as a promising strategy for the treatment of KRAS-mutant cancers." (PMID 39437162, 2025). "Inverted MYC/KRAS chimeras synergistically target KRAS mutant cancers." (PMID 40762837, 2025). "Specifically, the Ras family of GTPases is known for regulating actin cytoskeleton dynamics and cell migration, largely through the Ras subfamily of GTPases (HRAS, KRAS, NRAS), which have been found to be mutated in individuals with cancer and drive cancer metastasis." (PMID 41200767, 2025). "Notably, DEG-KRAS expression in mesenchymal stem cells (MSCs) exerted a bystander effect, leading to KRAS degradation and growth inhibition in co-cultured cancer cells." (PMID 41322195, 2025). "It is now wholly understood that KRAS oncogenic mutations facilitate autocrine signaling and interactions with the TME, specifically by immune response evasion and eventually resulting in cancer development, invasion, and progression." (PMID 40075634, 2025). "Similarly, KRAS-driven metabolic reprogramming enhances the survival of cancer cells under therapeutic stress." (PMID 40361439, 2025).
cancer (continued). "Additionally, SOS1 PROTACs based on SOS1 inhibitors or agonists have been developed, providing a new avenue for the treatment of KRAS-mutant cancers." (PMID 39437162, 2025). "In KRAS-mutant cancers with G12Ci-resistant cells, SOX2, SLC7A11 and SLC40A1 are downregulated." (PMID 41516092, 2025). "By elucidating the mechanisms KRAS modulates the microenvironment, we can generate novel insights that may inspire innovative therapies for KRAS-driven cancers." (PMID 40611261, 2025). "Additionally, LHF418 effectively inhibited KRAS‐RAF–ERK signaling and suppressed colony formation in KRAS‐driven cancer cells." (PMID 39898116, 2025). "Due to the important role of WEE1 in G1–S and G2–M cell-cycle checkpoints, high levels of baseline RS and DNA damage in KRAS-mutant cancer cells may confer sensitivity to WEE1 inhibition." (PMID 39807828, 2025). "We further tested all these mutations in 367 NSCLCs lacking driver mutations and 184 carcinomas carrying activating mutations in EGFR or KRAS genes." (PMID 40661875, 2025). "We validated them in vitro in different cancer cell lines with deregulated KRAS and/or MYC." (PMID 39457457, 2024). "An article with a higher LCR is more likely to be concerned about the field of KRAS-related cancer, which could find new trends from the article." (PMID 38706597, 2024). "Previous study demonstrated that combing FAK inhibition and KRAS G12C inhibitors could improve the treatment outcomes for KRAS G12C mutant cancers through the regulation of the FAK-YAP signaling." (PMID 38291516, 2024). "Another interesting observation is the upregulation of the cancer stem cell marker, a cluster of Differentiation 133 (CD133), which determines the poor overall survival in colorectal cancer (CRC) and is regulated by the mutation of KRAS or BRAF." (PMID 39056802, 2024). "From September 2016 to July 2022, a total of 133 patients with KRAS mutant cancers were identified." (PMID 38439805, 2024). "The possibility of pharmacologically targeting Id1 with trametinib in human cancers could offer a therapeutic alternative for those KRAS-mutant LUAD patients who poorly respond to ICIs or develop early acquired resistance." (PMID 38643157, 2024). "The mutated KRAS oncoprotein can keep KRAS in its GTP-bound ON state, driving cancer growth." (PMID 39594840, 2024). "To test this, we inhibited KRAS signaling in several mouse and human KRAS-mutant cancer cell lines." (PMID 38635884, 2024). "Interestingly, 81.8% of all KRAS mutations in CAC and 54.5% in sCRC affected codon 12, adding up to 68.2% in both cancer groups." (PMID 39390564, 2024). "Next, we discuss the methods and strategies cancers employ to resist KRAS inhibition." (PMID 38668053, 2024). "Therefore, the identification of mechanisms by which cancer cells evade treatment in mutant KRAS-driven tumors is of paramount importance." (PMID 39271958, 2024). "Therefore, KRAS has been given special attention and is of interest in understanding treatment strategies for human cancers." (PMID 38792177, 2024). "Gene set enrichment analysis (GSEA) Hallmark pathway analysis using a STAD dataset from TCGA revealed that TAGLN2 is involved in many signaling pathways associated with cancer, including apoptosis, hypoxia, MYC targets, KRAS signaling, and the reactive oxygen species pathway." (PMID 39168971, 2024). "Another example is a highly selective “monobody” against the active state of cancer-associated KRAS mutants that, when converted to a VHL-based bioPROTAC, selectively degraded the KRAS mutants, providing a more extended suppression of mutant KRAS activity than that achieved by the monobody alone." (PMID 39454955, 2024). "Inhibition of mutant KRAS challenged cancer research for decades." (PMID 38278976, 2024).